CD44 (CD44 molecule (IN blood group))
Diseases named in the same sentence as CD44 in open-access papers (continued):
Sharing a sentence is not in itself a finding about the gene and the disease.
colon carcinoma (continued). "CD44-positive colon cancer cells containing the variant exon 9 had significantly stronger colony–forming and tumor mass–forming abilities and resistance against anticancer drugs." (PMID 23800986, 2013). "Using the anti-CD44 standard form(s) antibody, as well as antibodies for each of the CD44 variant exons, we studied colon cancer cell lines by examining stained images of stem cells in the crypt of normal colon mucosa." (PMID 23800986, 2013). "CD44 transcript variants have been shown to be overexpressed and to mediate cell survival in colon cancer." (PMID 23227266, 2012). "In the present study, expression of alternatively spliced variants of CD44 and their cellular distribution have been investigated in human colonic tumours and in the corresponding normal mucosa, in addition to benign adenomatous polyps." (PMID 8695347, 1996). "We demonstrate that as well as being expressed in colonic tumour cells, the full range of CD44 variants, CD44v2-v10, are widely expressed in normal colonic crypt epithelium, predominantly in the crypt base." (PMID 8695347, 1996). "Additionally, human papilloma virus (HPV) infection is linked to CD44 overexpression in oropharyngeal cancers, and Helicobacter pylori infections are associated with increased CD44 expression in colon cancers." (PMID 39148690, 2024). "Although the variant of CD44 is unknown in the TCGA database, CD44 expression was significantly higher in right colon cancer than in left colon cancer as in our current study." (PMID 37098074, 2023). "However, in a comparative study, CD44 expression was found to be lower in ulcerative colitis-associated dysplasia and cancers than in sporadic colonic tumors." (PMID 35733095, 2022). "In humans, CD44 proteins are encoded by a highly conserved gene located on the short arm of chromosome 11 (11p13), whose expression is elevated in a wide range of malignant tumours, such as colon tumours, ovarian clear cell carcinoma and glioblastoma." (PMID 35264209, 2022). "Although O-glycosylated, sialofucosylated CD44v isoforms are the prevalent E-selectin ligands expressed by colon carcinoma cells, it has been shown that in hematopoietic cells, selectin ligand activity of CD44 is primarily associated with the N-glycosylated, sialofucosylated CD44s isoform." (PMID 34206154, 2021). "The high expression of PRDX2 was closely associated with CD133+CD44+ CCSCs in colon cancer." (PMID 33819194, 2021). "The LS1034 model with its inducible CD44v8-10 expression triggered by stromal fibroblasts in a particularly tumorigenic subpopulation seems to be a highly valuable tool to gain mechanistic insight into the functional role of this CD44 variant in colon cancer progression." (PMID 32685007, 2020). "CEA are glycosyl phosphatidyl inositol (GPI) cell surface anchored glycoproteins, who may cooperate with CD44 variant isoforms to mediate colon carcinoma cell adhesion to E- and L-selectin." (PMID 30303958, 2018). "From the total 244 switches, 10 occur in known cancer drivers, and several others have been associated before with cancer, like CD44, which has been observed to be relevant in colon cancer initiation, and SLC39A14, whose alternative splicing is regulated by WNT in colon cancer." (PMID 25578962, 2015). "Increasing CaSR levels, either by transfection (HT29CaSR) or by treatment with NPS R-568 reduced the stem-like phenotype in these cells by downregulating expression of pluripotency associated genes, SOX2, Nanog, Oct4, and the colon cancer stem cell marker, CD44." (PMID 25879211, 2015).
colon carcinoma (continued). "We report our findings on the importance of CD44 variant exon 9(v9) of stem cells in colon cancer." (PMID 23800986, 2013). "In addition, Lyn cooperates with a CD44-variant receptor in promoting chemoresistance in colon cancer cells." (PMID 23936469, 2013). "CD44 variant exon 9 plays an important role in colon cancer stem cells." (PMID 23800986, 2013). "Gene therapy using siRNA CD44 also caused in vitro and in vivo regression of HT colon cancer cells." (PMID 20736947, 2010). "Recently, studies have demonstrated that CD44 variant isoforms (CD44v) in LS174T colon carcinoma cells possess selectin binding activity, suggesting a broader role for CD44v in regulating tumor cell metastasis, particularly the event of migration across the vascular endothelium." (PMID 18350162, 2008). "5-FU treatment of human colon carcinoma cells resulted in the generation of 5-FU-resistant cells that are enriched for CD133+ tumor cells, and to a lesser degree, CD44+ tumor cells, suggesting that enrichment of colon CSCs might be an underlying mechanism of colon cancer chemoresistance." (PMID 27659530, 2016). "The adhesion molecules EpCAM, α2β1 and CD44 s were seen to mediate tumour cell adhesion to the peritoneum and might be particularly useful in the prevention of minimal residual disease in high-risk patients, such as patients with T4 colon tumours." (PMID 27074785, 2016). "Another approach used a [89Zr]Zr-anti-CD44 antibody targeting human and murine isoforms in CD44-positive colon cancer cells." (PMID 39753364, 2025). "The proteomic profiling of mucosal EVs from normal and colon tumors by LC-MS/MS revealed that high CD44 in tumor cells correlated with more EVs, and CD44 intensity marked CRC cells with differential capacity for EV release." (PMID 39851567, 2025). "The circulating CSC population from colon cancer patients has a distinct set of markers, including CD44." (PMID 41440277, 2025). "Identification of the DREAM transcriptional repression complex as a mediator of the differential response observed in EpCAM+/CD44+/CD166+ as compared to EpCAM+/CD44neg/CD166neg colon cancer cells following in vivo chemotherapy with irinotecan (CPT-11)." (PMID 39896677, 2025). "For in vitro studies, LOX1- and CD44- deficient MC38 and CT26 colon cancer cell lines, validated by RT-qPCR, were used to investigate the cellular uptake mechanism and macropinocytic activity of GHSACA using flow cytometry." (PMID 41488675, 2025). "Following siRNA-mediated knockdown of LOX1 and CD44 in murine colon cancer cell lines MC38 and CT26, gene expression levels were evaluated by RT-qPCR." (PMID 41488675, 2025). "In one study, ion exchange, immunoaffinity chromatography, and Western blot analysis were used as alternative methods to isoform-specific ELISA to examine the roles of different CD44 isoforms in colon cancer." (PMID 41440277, 2025). "PTPRD was also shown to be involved in colon cancer cell migration via a β-catenin/TCF/CD44 signalling pathway, whereas in lung cancer PTPRD appears to act as a tumour suppressor gene." (PMID 40871563, 2025). "For example, anti-CD44 antibody coated EVs packaged with doxorubicin were used to target the CD44+ CSC population in colon carcinoma." (PMID 38765006, 2024). "The results of our experiments with the PTX3 inhibitor WHC-001 supported the idea that disruption of the PTX3/CD44 interaction suppresses colon cancer progression in vivo." (PMID 38243273, 2024). "Li and Shen found that APS elevated caspase-9, caspase-3, and Bax protein levels, decreased Bcl-2 protein expression, and inhibited CD133 and CD44 co-positive colon cancer stem cell proliferation time- and concentration-dependently." (PMID 38515577, 2024). "Previous biological studies, followed by a meta-analysis, demonstrated that elevated CD44-positive colon cancer stem cells are an unfavorable prognostic factor in patients with CRC." (PMID 39502780, 2024).
colon carcinoma (continued). "PTPRD has also been shown to be involved in colon cancer cell migration via a β-catenin/TCF/CD44 signalling pathway, whereas in lung cancer, PTPRD appears to act as a tumour suppressor gene." (PMID 38339334, 2024). "These nanoparticles have demonstrated efficacy as a drug delivery system for API in treating colon tumors with high CD44 expression." (PMID 39416904, 2024). "The ratio of CD44+ CD62L+ central memory (TCM) cells was higher in hepatocellular carcinoma (HCC) tumors from MYC‐ON mice as well as in colon tumors from CT‐26 allograft mice after DU101 or DU102 treatment in comparison with DMSO treatment." (PMID 39225354, 2024). "The CD44+CD133+ colon cancer stem cell population was sorted, pre-exposed to RIS, and allowed to form spheroids, which were further assessed for their responses to chemotherapeutic 5-FU." (PMID 39518936, 2024). "This is valid for colon cancer, where a number of membrane proteins are known to be overexpressed (e.g., CD44 and its isoforms, folate receptors, HER1, and nucleolin)." (PMID 38543324, 2024). "Their results showed that this nano complex improved apoptosis and delay of tumor growth of CD44+ in HT29 cells of colon cancer." (PMID 38491817, 2024). "In an in vitro study of colon cancer CD133+/CD44+ cells, Li and Shen found that APS can induce apoptosis by activating the Fas death receptor pathway." (PMID 38515577, 2024). "We used cell sorting technology to isolate CD44-positive colon cancer cells from HCT-116 parental cells." (PMID 39502780, 2024). "In contrast to our study, previous reports demonstrated that deletion of the Cd44 gene inhibits initiation of colon carcinoma in Apc(Min/+) mice and oncogenic progression in the testis of RHAMM-deficient mice." (PMID 37174657, 2023). "We found that Piezo1 was highly expressed in the CD133+CD44+ colon cancer tissues, and patients with Piezo1high/CD133+CD44+ tumors were usually in the advanced stage." (PMID 37306789, 2023). "It is important to understand how CD44 and its various isoforms play a role in the stemness of colonic SCs because we2 and others have shown that SC overpopulation drives colon cancer development and growth." (PMID 37005380, 2023). "Compared with RNA-loaded DCs, DCs pulsed with lysates of colon cancer stem cells (CCSCs) isolated from CD44+ CT-26 colon cancer cells can evoke stronger anti-tumor immune responses against CCSCs." (PMID 36910604, 2023). "In this study, we found that Piezo1 was highly expressed in CD133+/CD44+ colon cancer tissues, and the Piezo1high/CD133+CD44+ population was associated with the clinical stage." (PMID 37306789, 2023). "In line with this, we detected higher expression of Piezo1 in the CD133+CD44+ CCSC fraction isolated from different colon cancer cell lines." (PMID 37306789, 2023). "CD44 has also been recognized as a marker for cancer stem cells and is frequently expressed in several malignancies, including ovarian and colon cancers." (PMID 36678845, 2023). "Unfortunately, the TCGA study on colon cancer using RNA-seq data doesn’t distinguish between the different CD44 isoforms so the correlation with CRC patient survival is for CD44s." (PMID 37005380, 2023). "Overall, HA-PLGA-API-NPs were an effective drug delivery platform for API in the treatment of colon cancers with high expression of CD44." (PMID 38005286, 2023). "Hyaluronic acid (HA) is a major extracellular matrix component and can specifically bind to CD44 on colon cancer cells." (PMID 38005286, 2023). "Human colon tumors are characterized by CD133+CD44+ cells, which are known as CSCs or tumor-starting cells." (PMID 36797277, 2023). "Consistent with the in-situ results, Piezo1 was overexpressed in the CD133+CD44+ fraction of multiple colon cancer cell lines, including HCT-116, HCT-8, SW480 and HT-29." (PMID 37306789, 2023).
colon carcinoma (continued). "Silica nanoparticles with hyaluronic acid (HA) and folic acid (FA) were developed to study dual-ligand targeting of CD44 and folate receptors, respectively, in colon cancer." (PMID 37685852, 2023). "With these observations in mind, CD44 has indeed been reported as carrier protein for STn in gastric and colon cancer." (PMID 37854601, 2023). "In the present study, we found that Piezo1 expression was high in the CD133+CD44+ CCSC fraction, and the Piezo1high/CD133+CD44+ colon cancer patients were in the advanced clinical stage." (PMID 37306789, 2023). "In colon carcinoma cells O-glycosylated CD44 can bind endothelial E-selectin, which in turns contributes to metastasis." (PMID 34693476, 2022). "In non‐Hodgkin's lymphoma and colon cancer, overexpression of CD44 has been correlated with advanced stage and poor survival." (PMID 35274800, 2022). "CD44v3 is modified by HS and has been shown to bind growth factors, promoting the binding of CD44 molecules to the cytoskeleton in colon cancer." (PMID 35936713, 2022). "LGR5 and CD44 are potential markers for isolating colon cancer stem cells (CSCs), which promote proliferation and tumor formation." (PMID 35269806, 2022). "Recently, CD44 has been used to recognize the CSCs for different kinds of cells, such as lung cancer, breast cancer, colon cancer, haematological cancer, and other cancers still under investigation." (PMID 36415383, 2022). "The 76 nm Au@Au core-shell NPs were then functionalized with hyaluronic acid (HA) to make them bind to an overexpressed HA receptor biomarker on the cell surface of human colon cancer cells, CD44 protein." (PMID 35164155, 2022). "Further, it was found that triptolide was able to in inhibiting CD133+/CD44+ colon cancer stem cell migration through repressing EMT program, which manifested as reducing the EMT-TFs, such as Snail, Slug, and twist expressions." (PMID 35308223, 2022). "ESRP1 downregulation in EpCAMlo colon cancer cells affects alternative splicing (AS) of CD44 and NUMB among a broad spectrum of downstream target genes." (PMID 36346211, 2022). "Meanwhile, immunohistochemical staining confirmed the decreased expression of β-catenin, α-sma, and CD44 in the liver metastases of colon cancer." (PMID 35837105, 2022). "TPL is a cytotoxic drug that showed an effect on positive CD133 and CD44 cancer cells by inhibiting the proliferation of colon cancer which leads to cell cycle arrest and induces apoptosis." (PMID 36415383, 2022). "CD133 and CD44 expression of HT-29 cells cultivated on TCP dishes was much lower than that of colon carcinoma cells in the permeation solution and recovered solution as well as migrated cells after permeation with NM-11 and PLGA/SK filters (p < 0.05)." (PMID 34641226, 2021). "The colon carcinoma cells in the permeation solution and recovered solution as well as migrated cells expressed high CD44 and CD133." (PMID 34641226, 2021). "Primary colon carcinoma cells (M-24) expressed relatively less CD44 than commercially available colon carcinoma cell lines, LoVo cells and HT-29 cells, although primary colon carcinoma cells (M-24) surely expressed the CSC (CIC) marker CD44." (PMID 34641226, 2021). "In our study, DRibbles were isolated from mouse colon carcinoma cell line CT-26 and CD44+ CCSCs by augmenting autophagy and inhibiting protein degradation with the treatment of rapamycin, bortezomib, and ammonium chloride." (PMID 34400894, 2021). "CD44 also induced EMT in colon carcinoma cells by upregulating MPP-14, stimulating cell invasion and migration." (PMID 34944493, 2021). "Another study showed the efficacy of atovaquone on EpCAM+CD44+ HCT-116 human colon cancer stem cells under hypoxia." (PMID 33562088, 2021). "89Zr-anti-CD44 demonstrated high-specific binding to HT29 human colon cancer cells and monocytic cells that showed CD44 expression." (PMID 33594192, 2021).
colon carcinoma (continued). "Surgical resection of the tumor in patients with gastric or colon cancer resulted in a significant decrease of CD44 concentration in serum." (PMID 34599251, 2021). "On the other hand, it has been reported that AUR reduced CD44 and BMI-1 expression in esophageal and colon cancer cells." (PMID 35432798, 2021). "Many studies reported that colon cancer progression and metastasis are influenced by the amount of CD44 protein expression." (PMID 34599251, 2021). "There were 26 different isoforms of CD44 detected in the colon cancer tissues, with the protein length ranging from 139 to 743 aa." (PMID 33907296, 2021). "Hyaluronic acid (HA) is another targeting ligand, which has been widely conjugated to the MSNs for specific recognition of CD44 overexpressing colon cancer cells." (PMID 34641857, 2021). "89Zr-anti-CD44 showed target-specific binding to CD44-positive HT29 colon cancer cells that was almost completely blocked by excess cold Ab, indicating high immuno-reactivity." (PMID 33594192, 2021). "An experiment demonstrates that colon cancer cells overexpressing CD44 as CSC marker are more sensitive to curcumin compared to CD44- cells." (PMID 34769099, 2021). "To determine the effects of SLCO4A1 has on colon cancer CD133+CD44+ × cells, we upregulated or knocked down the expression level of SLCO4A1 in CD133+CD44+-HCT116 cells, and the transfection effect was detected by western blot." (PMID 33958701, 2021). "PRDX2 is highly expressed in CD133/CD44-positive colon cancer tissues and spheroid CD133+CD44+ CCSCs." (PMID 33819194, 2021). "Western blot analysis showed an enhancement of the stem cell transcription factor Nanog, along with the colon cancer stem cell markers CD133 and CD44 in 5-FUR variant cells when compared to parental cells." (PMID 34571860, 2021). "In the present study, we identified that Zic2 enhances Wnt signaling and initiates the transcription of several novel downstream target genes, including cyclin D1, CD44, and Lgr5, which promote proliferation and stemness in colon cancer cells." (PMID 34099631, 2021). "In our present study, we demonstrated that PRDX2 is highly expressed in CD133/CD44-positive colon cancer tissues and spheroid CD133+CD44+ CCSCs." (PMID 33819194, 2021). "Immunocytochemical analysis of CD133, CD44 and Nestin expression of colon adenocarcinoma cell line HT-29 and colon carcinoma cell line HCT-116 only revealed slight expression of these CSC-markers." (PMID 32927768, 2020). "Knockdown of CD44 glycoform haematopoietic cell E‐/L‐selectin ligand (HCELL) in colon carcinoma cells resulted in reduced binding to HUVECs and increased rolling speed." (PMID 33210465, 2020). "Findings from this study suggest that oxaliplatin resistance in colon cancer cells involves the activation of SphK1/S1P/S1PR2 signaling axis that activates ERK signaling pathway resulting in the induction of CD44 expression." (PMID 32456134, 2020). "CD44v6, the CD44 isoform mostly involved in cancer cell migration and invasion, has been identified as a functional biomarker and therapeutic target in colon cancer stem cells." (PMID 33227095, 2020). "Our data correlate with data from colon cancer cell lines derived from the same patient, in which the early stage cells were almost all CD44 positive, while only a very small percentage were CD133 positive." (PMID 32188032, 2020). "It has been shown that PKM2 activity is negatively regulated by the increased presence of CD44 (a known cancer biomarker), and this effect mediates the aggressive glycolytic phenotype of colon cancer cells." (PMID 32517019, 2020). "Increased expression levels of SphK1 and CD44 were observed in oxaliplatin-resistant colon cancer cells in comparison with parental cells." (PMID 32456134, 2020). "As mentioned in the introduction, the expression of CD133 and CD44 are well-characterized markers of CSC-like cells in colon cancer." (PMID 32423158, 2020).